CCDC59 (coiled-coil domain containing 59)
Description:
Component of the transcription complexes of the pulmonary surfactant-associated protein-B (SFTPB) and -C (SFTPC). Enhances homeobox protein Nkx-2.1-activated SFTPB and SFTPC promoter activities.
Synonyms: BR22; TAP26; HSPC128
Tractability: Antibody: the Human Protein Atlas places it where antibodies can reach. PROTAC: ubiquitination databases record sites on it; its protein half-life has been measured.
Gene: Protein-coding gene on chromosome 12 (82,223,681 to 82,358,805, reverse strand). Ensembl gene ENSG00000133773.
Subcellular location: Nucleus
Subcellular location (Human Protein Atlas): Nucleoli; Nucleoli rim; Nucleoplasm; Plasma membrane
Pathways (Reactome):
Metabolism of proteins: Surfactant metabolism
Gene Ontology:
Molecular function: protein binding; RNA binding
Cellular component: nucleoplasm; nucleus
Genetic constraint (gnomAD): Loss-of-function variants: 19 observed, 23.53 expected, observed/expected ratio (o/e) 0.81, 90% interval 0.56 to 1.18. The upper end of that interval is the gene's LOEUF score, 1.18, which puts it in group 5 of 6, group 1 being the genes least tolerant of losing a copy. Missense variants: 316 observed, 250.14 expected, observed/expected ratio (o/e) 1.26, 90% interval 1.15 to 1.39. Synonymous variants: 112 observed, 92.95 expected, observed/expected ratio (o/e) 1.21, 90% interval 1.03 to 1.41.
Homologues: Orthologues: chimpanzee CCDC59 (96% identical), macaque CCDC59 (89% identical), rabbit CCDC59 (76% identical), pig CCDC59 (75% identical), guinea pig CCDC59 (75% identical), dog CCDC59 (72% identical), rat Ccdc59 (70% identical), mouse Ccdc59 (69% identical), zebrafish ccdc59 (37% identical), tropical clawed frog ccdc59 (32% identical), Caenorhabditis elegans F10E9.11 (13% identical).